IL18 (interleukin 18)
Diseases named in the same sentence as IL18 in open-access papers (continued):
Sharing a sentence is not in itself a finding about the gene and the disease.
melanoma (continued). "For instance, a high dose of IL-18 significantly reduced the metastasis of tumors derived from B16F10 melanomas and CT26 colon carcinoma through an increase in PD-1 expression in splenic NK cells." (PMID 37501379, 2023). "Blocking IL-18 with a soluble factor can decrease the adhesion of melanoma cells by inhibiting this mechanism." (PMID 37240247, 2023). "Although Erdr1expression was not analyzed in our previous study, it is possible that the balance between Il18 and Erdr1 expression is important for the treatment of melanoma." (PMID 38139000, 2023). "IL-18 is also known to play a key role in melanoma regulation and is one of the AIM2 inflammasome components, recently recognized as a potential target for melanoma treatment." (PMID 35205739, 2022). "Another replication-competent adenoviral vector encoding IL-18 (ZD55-IL-18) was used for human melanoma A375 cells and nude mouse A375 tumour xenografts treatment alone or together with melanoma-approved drug—dacarbazine (DTIC)." (PMID 36140243, 2022). "This enzyme cleaves and promotes the maturation of pro-inflammatory cytokines such as interleukin-1β (IL-1β) and interleukin-18 (IL-18) by macrophages, dendritic cells, and some tumor cells, such as human melanomas." (PMID 36144933, 2022). "The administration of IL-18 to mice bearing melanoma increased the accumulation of M-MDSC in the tumor microenvironment." (PMID 35739593, 2022). "Scientific studies say that in IL‐18 overexpressed murine model with malignant melanoma, it reduces the rate of tumor development, enhances apoptosis in tumor cells and lessens lung metastasis." (PMID 34196131, 2022). "Previously, our group demonstrated that systemic expression of IL-12+IL-18 was capable of inducing a strong antitumor effect against 2 different tumor cells lines in vivo (B16, melanoma and 3LL, lung carcinoma)." (PMID 36330506, 2022). "Increased IL-18 levels in the serum of cancer patients correlate with malignancy, and IL-18 acts as a crucial factor for cell migration in gastric cancer and melanoma." (PMID 34912237, 2021). "Several clinical trials testing the antitumor efficacy of IL-18 have been conducted in lymphomas and melanoma." (PMID 34114949, 2021). "Second, several cancer cell lines, such as murine colon (CT26), melanoma (B16F10) or human breast (MDA-MB-231) cancer cells or nasopharyngeal cancer patient tumors have been reported to secrete IL-18." (PMID 33261061, 2020). "IL-18 also enhances anti-PD1 antitumor effect in murine colon cancer (CT26) or melanoma (B16F10) peritoneal dissemination models in a NK and CD8+ T cell-dependent manner." (PMID 33261061, 2020). "Another oncolytic adenovirus expressing IL-12 (RdB/IL-12) inhibits tumor growth in murine melanoma lines by 95%, while adenovirus expressing both IL-12 and IL-18 (RdB/IL-12/IL-18) inhibits growth by 99%." (PMID 32050597, 2020). "IL-18 CAR-T cells against CD19 + melanoma cells showed better anti-tumor efficacy in comparison with CAR-T cells without IL-18 release." (PMID 33167514, 2020). "IL‐18 was reported to enhance the metastatic ability of melanoma cells via the generation of ROI and activation of the MAPK pathway." (PMID 32347623, 2020). "In a phase I clinical trial, twenty-one RCC patients, six melanoma patients and one patient with Hodgkin lymphoma were given IL-18 in doses ranging from 3 to 1000 μg/kg." (PMID 31492049, 2019). "Our study found that IL18 mRNA expression in melanoma tumor tissue was lower than that in normal tissues and higher IL18 expression leads to increased survival rates." (PMID 31731729, 2019). "For instance, administration of IL-18BP significantly suppressed melanoma cell metastasis to the liver by preventing IL-18-induced expression of adhesion molecules such as vascular cell adhesion molecule-1 (VCAM-1) on hepatic sinusoidal endothelial cells." (PMID 31231372, 2019).
melanoma (continued). "In conclusion, this study provides the first evidence for the potential of IL-18 expression as a biomarker for predicting melanoma prognosis and its correlation with infiltration by cytotoxic CD8+ T and NK cells." (PMID 31731729, 2019). "Collectively, these data-driven results suggest that IL18 expression is significantly downregulated in melanoma cells and is positively correlated with patient survival." (PMID 31731729, 2019). "Melanoma cells have been shown to produce IL-18 spontaneously, which is related to the immune escape of melanoma through the enhancement of metastatic ability and tumor growth." (PMID 31731729, 2019). "In this study, we investigated IL-18 expression and its correlation with patient survival and immune cell infiltration in melanoma using cancer gene expression data publicly available through various databases." (PMID 31731729, 2019). "Adoptive transfer of T cells engineered with a melanoma-specific T cell receptor (TCR) and inducible IL-18 resulted in enhanced antitumor T cell responses, hence suppressing melanoma growth in vivo." (PMID 31492049, 2019). "Relative IL18 expression was significantly downregulated in melanoma tissue compared to normal tissue in the Riker and Talantoy melanoma datasets (P = 7.80 × 10−4 and 0.021, respectively)." (PMID 31731729, 2019). "To investigate the mechanisms and relationship between IL18 and good prognosis in melanoma, we focused on immune cell infiltrates in the melanoma tumor environment." (PMID 31731729, 2019). "Exogenous IL-18 increases cell migration in the melanoma cell line B16F10, and cell adhesion in both murine and human melanoma cell lines, implying that IL-18 enhances malignant properties in melanoma cell." (PMID 31731729, 2019). "IL-12 co-expressing B7-1 (YKL-IL12/B7), IL-18 (RdB/IL-12/IL-18), and 4-1BBL oncolytic adenoviruses have been generated to evaluate the antitumor effect of the virus in a murine melanoma B16-F10 tumor model." (PMID 29857493, 2018). "The anti-tumor potential of several cytokines such as interleukin 2 (IL-2), interferon γ (IFN-γ), granulocyte-macrophage colony-stimulating factor (GM-CSF), IL-12 and IL-18 have been evaluated for the treatment of canine melanoma patients." (PMID 29534457, 2018). "In our investigation, the mRNA level of IL-1α, IL-1β, and IL-18 were all decreased, indicating the suppression of the inflammatory environment in human melanoma." (PMID 30149677, 2018). "Recently, IL‐18 was shown to be involved in therapy for melanoma 37, renal cell carcinoma 38, and lung cancer." (PMID 30524946, 2018). "Studies have confirmed that IL-1β, IL-1α, IL-6, IL-8, IL-18 and their receptors are permanently expressed in malignant melanoma cells, suggesting that chronic inflammation exists during the melanoma development." (PMID 30149677, 2018). "As such, systemic injection of IL-18 protein and over-expressing IL-18 have been reported to enhance T cell response and NK cell function in several tumor models such as B16 melanoma." (PMID 28955343, 2017). "Inhibition of NLRP3 inflammasome by thymoquinone resulted in reduced secretion of IL-1β and IL-18 with the suppressed the migration of melanoma." (PMID 28360909, 2017). "Studies have demonstrated that IL-18 enhances the migration of murine melanoma cells via the generation of “reactive oxygen species” (ROS) and the MAPK pathway." (PMID 27941650, 2016). "On the other hand, NK cells cultured with IL-15/IL-18 maintained their cytolytic activity against melanoma targets in the presence of both inhibitors." (PMID 27563819, 2016). "Particularly, ERDR1 plays an important role in cancer progression due to its suppression of tumor cell migration and metastasis in melanoma and gastric cancer, while IL-18 enhances these effects in these tumor types." (PMID 26901187, 2016).
melanoma (continued). "In our previous studies, we found that erythroid differentiation regulator 1 (ERDR1) is negatively regulated by IL-18 and has an anti-cancer effect on murine melanoma through the inhibition of migration and invasive activity, in contrast to IL-18." (PMID 26901187, 2016). "A representative proinflammatory cytokine, interleukin (IL)-18, exerts procancer effects in melanoma." (PMID 26784177, 2016). "Melanomas developed through inflammation-dependent mechanisms have high metastatic potential that is dependent on IL-18, which can activate the STAT3 pathway." (PMID 27941650, 2016). "IL-18, a representative pro-inflammatory cytokine, increases cell migration in human gastric cancer and murine melanoma." (PMID 27589563, 2016). "In the study, Erdr1 expression was found to be negatively regulated by IL-18, which has a pro-cancer effect on melanoma." (PMID 27941650, 2016). "The significant contribution of IL-18 during melanoma progression enabled us to investigate the role of IL-32 in melanoma migration in this study." (PMID 27589563, 2016). "The administration of IL-18 also induced anti-tumor immunity in mice bearing B16 melanoma tumors expressing B7-1 (CD80)." (PMID 26378020, 2015). "IL-18 can also suppress the anti-metastatic effect of NK-cells and IL-18 depletion boosts immune surveillance function of NK cells in B16-F10 melanomas and CT26 colon cancers." (PMID 24474192, 2014). "In opposition to the results in the previous section, endogenous IL-18 from melanoma cells was also found to inhibit NK cell-mediated killing of melanoma cells by upregulating Fas ligand expression." (PMID 24795727, 2014). "In vitro, secreted factors from the melanoma cell line induced IL-18-dependent upregulation of VCAM-1 on hepatic sinusoidal endothelial cells, as well as IL-1β secretion." (PMID 24795727, 2014). "In concert with these data, administration of exogenous IL-18 led to an increase of adherent melanoma cells to sinusoidal endothelial cells." (PMID 24273542, 2013). "Other studies showed that administration of IL-18 binding protein, which blocks IL-18, before injection of B16 melanoma into the spleen reduced metastasis to the liver." (PMID 24273542, 2013). "It was also shown that administration of IL-18 induced anti-tumor immunity in mice bearing B16 melanoma tumors expressing B7-1 (CD80)." (PMID 24273542, 2013). "The mechanism involved IL-18 blockade at three levels: First, resveratrol prevented IL-18 augmentation in the blood of melanoma cell-infiltrated livers." (PMID 21569399, 2011). "Not surprisingly, both adhesion and proliferation were upregulated in IL-18-treated melanoma cells via hydrogen peroxide-dependent NF-kappaB activation, which was inhibited by RVL in this tumor model." (PMID 21569399, 2011). "We demonstrated that resveratrol prevented inflammation-dependent hepatic melanoma metastasis by inhibiting both secretion of IL-18 from tumor-affected liver and effects of hepatic IL-18 on melanoma cells." (PMID 21569399, 2011). "Interleukin-18 (IL-18) has been demonstrated in vivo and in vitro to promote liver metastasis by enhancing melanoma cell adhesion to the hepatic sinusoidal endothelial cells via microvascular VCAM-1 (vascular cell adhesion molecule-1) expression." (PMID 16336680, 2005). "Moreover, the ability of WT IL18 to limit the in vivo progression of B16-F10 melanomas was lost in immunodeficient mice." (PMID 40263267, 2025). "IL-18 may also play a role in metastasis, as it has been shown to enhance the migratory phenotype of melanoma cells." (PMID 38391959, 2024). "However, other studies have reported that NLRP3 inflammasome activation and the production of IL-1β and IL-18 can promote melanoma growth." (PMID 39769450, 2024). "One study has shown that Erdr1 is negatively regulated by IL18 in melanoma cells." (PMID 38139000, 2023).
melanoma (continued). "Furthermore, in vivo neutralization of IL-18 with IL-18BP reduced melanoma metastases into the liver in a mouse model and il18-/- mice exhibited less tumor growth in a multiple myeloma mouse models." (PMID 37298187, 2023). "Moreover, exogenous IL18 supports melanoma invasion through MAPK activation (with increased ERK phosphorylation) and in a reactive oxygen intermediate (ROI)-depended manner." (PMID 36123693, 2022). "The role of IL-18 expression in melanoma patients has been previously reported, but the interplay with the autoimmunity is highlighted here for the first time, in the melanoma setting." (PMID 35205739, 2022). "Therefore, in this study, we investigated the expression of IL-18 and its relevance on patient survival in melanoma." (PMID 31731729, 2019). "Collectively, this study provides the first evidence that IL18 expression has prognostic value for melanoma patient survival and is strongly correlated with CD8+ T and NK cell infiltration, suggesting the role of IL-18 as a biomarker for predicting melanoma prognosis." (PMID 31731729, 2019). "IL18 mRNA expression was found to be significantly lower in melanoma tissues than normal tissues." (PMID 31731729, 2019). "Therefore, the infiltrating immune cells seem to be a major source of IL-18 in the melanoma tumor environment." (PMID 31731729, 2019). "Therefore, our systematic analysis provides an integrated understanding of the potential role of IL-18 in melanoma and its use as a useful biomarker for the prognosis of melanoma patients." (PMID 31731729, 2019). "Therefore, a systematic analysis of IL-18 expression and the correlation between IL-18 and patient survival in melanoma is definitely needed in order to comprehensively understand the roles of IL-18 in the body of melanoma patients." (PMID 31731729, 2019). "However, in melanoma it has been observed that IL-18 enhances the antitumor response by inducing tumor-infiltrating CD8+ T lymphocytes." (PMID 31554368, 2019). "In vitro studies show the direct effects of exogenous IL-18 on melanoma." (PMID 31731729, 2019). "Additionally, decreasing mRNA levels of IL-1α, IL-1β, and IL-18 further proved the negative regulation of CP on the melanoma inflammatory environment." (PMID 30149677, 2018). "The role of IL-18 in melanoma progression awaits discoveries." (PMID 28360909, 2017). "The relationship between melanoma and IL-18 has been widely studied." (PMID 27941650, 2016). "It has been shown in new experimental melanoma models that IL-18 may convert conventional Kit− into Kit+ NK cells that have immunosuppressive role." (PMID 25889680, 2015). "So downregulation of NKG2D after IL-18 in vitro treatment shown in this study could facilitate escape of melanoma cells from NKG2D-mediated killing by NK cells." (PMID 25889680, 2015). "In B16 melanoma models IL-18 acts as both an immunosuppressive and prometastatic factor." (PMID 24273542, 2013). "In an intravenous model of B16 melanoma IL-18 was shown to upregulate PD-1 expression on NK cells." (PMID 24273542, 2013). "Second, because IL-18 regulates melanoma metastasis occurrence via VLA-4-dependent B16M cell adhesion to HSE, the effects of RVL on IL-18 secretion and VCAM-1 expression by hepatic sinusoidal cells, and on the cancer cell response to IL-18 were studied in vitro." (PMID 21569399, 2011). "A hepatic melanoma metastasis model where a majority of metastases are generated via interleukin-18-dependent mechanisms was used to test whether anti-inflammatory properties of resveratrol can interfere with mechanisms of metastasis." (PMID 21569399, 2011). "The effect of resveratrol on melanoma cell activation by IL-18 was also studied." (PMID 21569399, 2011). "Our current results show that RVL abolished H2O2 production from IL-18-treated melanoma cells." (PMID 21569399, 2011).
melanoma (continued). "Because IL-18 promotes the adhesion of B16 melanoma cells to the hepatic microvascular endothelium via VCAM-1-dependent mechanism, we next studied the effect of RVL on the VCAM-1 expression level in primary cultured hepatic endothelial cells given either recombinant murine IL-18 or B16M-CM." (PMID 21569399, 2011). "According to our results, RVL-dependent metastatic growth inhibition it may depend in part on direct anti-proliferative effects of RVL on IL-18-dependent melanoma cells." (PMID 21569399, 2011). "Indeed, activation of the P2RX7/IL-18 axis with HEI3090 sensitized lung and melanoma tumors to immunotherapy, cured 80% of mice and protected them from a tumor rechallenge, highlighting the potency of IL-18 in generating long lasting memory T cells in tumor models." (PMID 37298187, 2023). "Moreover, our results provide evidence that IL18 could be considered a critical biomarker in myeloid cells, which was further considered a protective predictor in melanoma." (PMID 37620327, 2023). "Indeed, it was shown that daily systemic administration of rIL-18 had antitumor effects, whereas once weekly or bi-weekly administration favored lung metastases of melanoma cells and induced a strong immunosuppressive environment, hinting that the levels of IL-18 are critical for its effect." (PMID 37298187, 2023). "In addition to the possible diagnostic role reported in the previous figures, such data indicate that NOD2 and IL-18 expression levels may also have a prognostic value in melanoma." (PMID 35205739, 2022). "Thus, IL-18 improved the anticancer activity of dacarbazine in malignant melanoma." (PMID 31492049, 2019). "Also, overexpression of IL-18 in a mouse model of malignant melanoma has been shown to increase tumor cell apoptosis, inhibit tumor growth, reduce lung metastasis, and inhibit angiogenesis, implying that IL-18 shows systemically a significant anti-cancer effect in the body." (PMID 31731729, 2019). "However, Erdr1 produces the opposite effect on IL-18 in melanoma and gastric cancer." (PMID 27941650, 2016). "Therefore, together with proinflammatory effects of IL-18 on HSE cells, melanoma cell function might also be affected by HSE-derived IL-18 in the microenvironment of tumor-activated liver." (PMID 21569399, 2011). "However, IL-18 expression was found to be reduced in ultraviolet radiation-induced melanoma." (PMID 24281094, 2010). "Follow-up samples indicated that after the removal of malignant melanoma, the serum levels of GM-CSF, IFN-γ, MCP-1, IL-18, and IL-2 increased significantly." (PMID 40711287, 2025). "IL-1β and IL-18 enhance the expression of adhesion molecules, like VCAM-1, facilitating melanoma cell attachment to blood vessel walls and promoting their migration to other organs." (PMID 39329914, 2024). "In a human melanoma xenograft model, additional transduction of NY-ESO-1-specific TCR-T cells expressing active IL18 resulted in a significant increase in the number of viable T cells in peripheral blood and inhibition of tumor progression." (PMID 38570883, 2024). "M1-type macrophages are involved in the tumor immune process of melanoma by secreting cytokines, such as IL-1β, TNF-α, IL-12 and IL-18." (PMID 37762054, 2023). "Histologically, melanoma tissues had fewer positive cells percentage of pyroptosis-related genes (PRGs), GZMA, GSDMB, NLRP1, IL18, and CHMP4A in epidermal than in normal skin." (PMID 37620327, 2023). "Previously, it was described that IL-18 is able to increase the expression of VCAM-1 in the hepatic sinusoidal epithelium, promoting the adherence of melanoma cells." (PMID 37240247, 2023). "Compared to HaCaT, melanoma cells showed lower levels of GSDM A, GSDM C and IL18 and higher levels of NLRP6." (PMID 36674798, 2023). "Histologically, melanoma tissues had fewer positive cells percentage of PRGs, GZMA, GSDMB, NLRP1, IL18, and CHMP4A in epidermal than in normal skin." (PMID 37620327, 2023).